CD4 (CD4 molecule)
Diseases named in the same sentence as CD4 in open-access papers (continued):
Sharing a sentence is not in itself a finding about the gene and the disease.
breast cancer (continued). "In the TME of breast cancer, myCAFs were shown to promote an immunosuppressive environment by attracting and retaining CD4+CD25+ T-cells through the ligands tumor necrosis factor receptor superfamily member 4 (OX40L), PD-L2, and the adhesion molecule junctional adhesion molecule B (JAM2)." (PMID 36010901, 2022). "Finally, we explored the association of CD4+ and CD8+ T cells with cPLA2 (PLA2G4A) gene expression in invasive basal-like breast cancer patients using the TIMER database." (PMID 35135586, 2022). "In addition, Datta and colleagues evaluated the CD4+ Th1 immune response in patients with primary invasive HER2-positive breast cancer treated with trastuzumab plus chemotherapy." (PMID 36551522, 2022). "The results showed that in normal and tumor samples, the TILs with significantly statistical differences included M2 macrophages, M0 macrophages, resting memory CD4 T cells, naïve B cells, and resting mast cells between breast normal tissues and breast cancer tissues." (PMID 35317079, 2022). "In breast cancer patients, the increase in memory CD4 T and plasma cells seems to be conducive to the prolongation of survival (disease-free survival or overall survival), while the increase in M2 macrophages, activated NK cells, Tregs and activated mast cells is related to the decrease in survival." (PMID 36611857, 2022). "Similarly, it also showed that antitumor immune cells such as B cells, CD8+ T cells, CD4+ effector T cells and dendritic cells were enriched in Th2-low group based on TCGA breast cancer database." (PMID 36564797, 2022). "It was reported that a high expression of CD4+ T cells might imply progression of breast cancer and patients with higher expression of CD4+ T cell had worse cancer specific OS in breast cancer." (PMID 35368651, 2022). "TILs are mainly CD8+ cytotoxic T cells, CD4+ helper T cells and B cells in breast cancer." (PMID 36483045, 2022). "In addition, the HER2-specific response of circulating CD4+ T cells after anti-HER2 treatment has been correlated with HER2+ breast cancer recurrence." (PMID 36135052, 2022). "CD4+T cells were isolated using immunomagnetic beads from draining lymph nodes and spleens from tumor bearing C57Bl/6 mice, 28 days post-injection of Py230 syngeneic breast cancer cells." (PMID 33918403, 2021). "Another study on breast cancer identified a significant increase in the ratios of MDSCs, Tregs, and “exhausted” CD4+ and CD8+ T cells in SN, indicating that SN has a profound immunosuppressive microenvironment, which becomes more profound in the presence of metastases." (PMID 34458377, 2021). "Some research groups had pointed out that CD4+TN often indicated poor prognosis of breast cancer." (PMID 34777388, 2021). "What specific role and colocalization these CD4+ TRM might have in breast cancer and if their presence favors a good response to (immuno-)therapy is still unclear." (PMID 33467084, 2021). "In addition, higher numbers of naive CD4+ T cells have been associated with poor prognosis in human breast cancer and these CD4+ cells are likely the main source of immunosuppressive Tregs in breast cancer." (PMID 34602068, 2021). "Breast cancer associated TREG cells show a significantly higher expression of CTLA-4 and tumor necrosis factor receptor superfamily, member 4 (TNFRSF-4, also known as OX-40) on their membranes compared to other CD4+ and CD8+ T cells." (PMID 33467084, 2021). "On the one hand, a maintenance immunotherapy protocol based on low-dose IL-2 and oral 13-cis retinoic acid (RA) has been shown to increase lymphocytes and NK cell levels as well as CD4+/CD8+ ratio in breast cancer patients with a clinical benefit from chemotherapy." (PMID 33572626, 2021). "We speculated that high-expressed SKA3 might impact the eosinophil and activated CD4 T cells, triggering a disadvantageous immune response, leading to a poor prognosis in breast cancer." (PMID 34993016, 2021).
breast cancer (continued). "Importantly, the high salt expanded CD4+T cells retained tumor-specificity, as demonstrated by higher in vitro cytotoxicity against Py230 breast cancer cells and reduced in vivo syngeneic tumor growth." (PMID 33918403, 2021). "The study showed that CD4+ follicular helper T-cell infiltration could be used to predict breast cancer survival." (PMID 34671397, 2021). "The proportional increase of CD4+ T cells in all breast cancers compared to normal tissue is higher than the proportional increase of CD8+ T cells, consistent with their central role in maintaining the delicate balance between protective and inflammatory immune responses in the tumor." (PMID 33467084, 2021). "To identify factors that can induce CD177 expression on Treg cells, we purified human PB Treg cells or CD4 Tconv cells from breast cancer patients, or splenic Treg cells or CD4 Tconv from MC38 tumor-bearing mice, either non-stimulated (ns) or treated with anti-CD3/CD28 and IL-2." (PMID 34599187, 2021). "Therefore, we further analyzed the association between the methylation levels of RUNX genes and immune cell infiltration (B cells, CD8+T cells, CD4+T cells, macrophages, neutrophils, and dendritic cells) in breast cancer using the GSCA database." (PMID 34485309, 2021). "Naringenin could block the secretion of TGF-β1 from breast cancer cells, reducing the percentage of CD4+ CD25+ Foxp3 + T cells and suppressing tumor cell migration as well as lung metastasis." (PMID 33572626, 2021). "Thus, aged breast cancer patients receiving chemotherapy showed an accumulation of CD4+ T effector memory re-expressing CD45RA." (PMID 34386013, 2021). "scRNAseq of CD4+ T cells from several breast cancer subtypes reported that CD4+ TEM and TCM clusters exhibit variable levels of gene expression involved in type I and II interferon response, hypoxia, and anergy, indeed indicating a different signaling and role in the tumor." (PMID 33467084, 2021). "To clarify whether in human cancers antigen-experienced Teff or memory Tconv contribute to the Treg repertoire in vivo, we compared the TCR repertoires of antigen-experienced TA-specific CD4+Teff clones and Treg in PB of breast cancer patients." (PMID 33602930, 2021). "To gain insights into the potential systemic antitumor efficacy of ISIM treatment of mice bearing orthotopic mammary tumors with brain metastasis, we evaluated the phenotype of CD4+ and CD8+ T cells in the spleens of untreated or ISIM-treated mice by flow cytometry." (PMID 34754037, 2021). "The objective is to check whether any subpopulation with a specific function can be identified among these CD4 T cells, and to link it to the immune response against breast cancer." (PMID 33830183, 2021). "TSLP at distant sites of breast cancer leads to robust antitumor immunity by CD4+ Th2 cells." (PMID 33652749, 2021). "Moreover, the recruitment of CD4 + CD25 + Treg cells to CAFs also depends on the chemokine CCL5 according to studies examining breast cancer." (PMID 34635121, 2021). "CD4 + and CD8 + lymphocytes play crucial parts in determining cancer treatment and high intra-tumoral lymphocyte counts were found to be associated with better survival in breast cancer patients." (PMID 32533334, 2020). "When we analyzed associations between fatty acid groups and subsequent breast cancer risk by tumor tissue expression subtype, no convincing evidence of heterogeneity was observed by CD4, CD20, CD163, or COX-2 expression." (PMID 32698885, 2020). "Combined with the results of these previous clinical studies, the data reported here may be used to further explore the characteristics of the CDR3 repertoires and assess the breast cancer microenvironment of CD4+CD25+Tregs." (PMID 33029539, 2020). "However, elevated ACE2 is significantly correlated with immune infiltrating levels, including those of CD8+ T cells, CD4+ T cells, macrophages, neutrophils, and DCs in multiple cancers, especially in lung and breast cancer patients." (PMID 33195415, 2020).
breast cancer (continued). "The ratio of CD4+/CD8+ was significantly decreased in TFG or TFMG-treated groups relative to the control in allograft LLC tumor model as well as in the MMTV-PyMT spontaneous breast cancer model." (PMID 32928251, 2020). "A decrease in CALM1 has been reported for CD4+ TIL in breast cancer, and CALM3 expression in TIL has been shown to be higher in extensively infiltrated tumors vs minimally infiltrated tumors suggesting a possible association between CaM levels and tumor infiltrating abilities of T cells." (PMID 32184726, 2020). "Associations between fatty acids and breast cancer risk did not vary substantially by tumor CD4, CD20, CD163, or COX-2." (PMID 32698885, 2020). "The study may be used to further explore the characteristics of the CDR3 repertoires and determine the source of the CD4+CD25+ T cells in the breast cancer microenvironment." (PMID 33029539, 2020). "We hypothesize that time resolved microscopy of CD4 + T-cell influence on trastuzumab treated HER2 + breast cancer will highlight the interaction between immune cells and cancer cell response to therapy." (PMID 33292267, 2020). "M2 macrophages and CD4+ Th2 present in the tumor microenvironment possibly mediate tumor progression by favoring invasion and metastasis formation, as it has been shown in a breast cancer model." (PMID 33042121, 2020). "CD4+ Tem, CD8+ Tcm, CD8+ T-cells, CD8+ naive T-cells, and B cells were associated with better prognosis whereas CD4+ naive T-cells were negatively associated with prognosis for breast cancer patients." (PMID 32728493, 2020). "However, CD4 + data are very limited, and more prospective studies are needed to confirm their prognostic value in breast cancer." (PMID 32533334, 2020). "Indeed, we find lower breakpoint pairwise-distance values in the single-nuclei derived from the T-cell leukemia compared to both CD8+/CD4+ T-cells and T-cells found in breast cancer biopsies." (PMID 32401198, 2020). "Interestingly, in this study, HR-negative breast cancers revealed high CD4+ TIL infiltration in both in situ and invasive components of the same tumors with no statistical difference." (PMID 32216826, 2020). "In our study, high MALAT-1 expression levels were associated with low immune cell infiltration (e.g., CD4+ and CD8+ T cells), which may explain the correlation between MALAT-1 and poor prognosis in patients with breast cancer." (PMID 32700729, 2020). "It has also been hypothesized that the risk allele for the two top breast cancer candidate SNPs, rs2787486 and rs244353, affected gene expression of STXBP4 and CD4 memory cells." (PMID 32115800, 2020). "Bregs in the context of breast cancer could induce the conversion of resting CD4+ T cells to Tregs to facilitate the lung metastasis." (PMID 33083479, 2020). "Regulatory CD4+ T cell (Treg), a subset of tumor-infiltrating lymphocytes (TILs), are known to suppress anticancer immunity but its clinical relevance in human breast cancer remains unclear." (PMID 33086518, 2020). "Furthermore, HER2(+) breast cancer was reported to have a higher proportion of CD4+ T cells and Treg than the luminal breast cancer subtype." (PMID 31143539, 2019). "In order to validate our findings in ex-vivo tumor tissue samples, we isolated intratumoral and peripheral pDCs from patients with breast cancer, co-cultured them with autologous peripheral CD4+CD45RA+ T cells and measured the fraction of FoxP3+ cells by flow cytometric analysis." (PMID 31440253, 2019). "Moreover, we found that these gene signature also correlated with an increased OS and with a higher level of tumor immune infiltrates (B cells, CD8+ T cells, CD4+ T cells, neutrophils, and dendritic cells) in basal-like breast cancer." (PMID 31998644, 2019).
breast cancer (continued). "SK-BR-3 breast cancer cells co-cultured with CD4+ T-cells from breast cancer patients primed with Class II HER2 peptides resulted in senescence and apoptosis of SK-BR-3 cells, evidenced by increased SA-β-gal staining (p < 0.001) and p15INK4b and cleaved caspase-3 expression (CD4+ - DC H, 3)." (PMID 29796172, 2018). "Many of the highly published disease-gene associations may have been studied for reasons that would not be directly reflected in gene expression analysis, including BRCA1 in breast cancer and CD4 in human immunodeficiency virus." (PMID 29358745, 2018). "In addition, Th1 cells in the early stages were changed to Treg and Th17 cells in the late stages of the breast cancer development as instructed by CD4+ T cells." (PMID 30120362, 2018). "In a compendium of four human breast cancer datasets, we show a clear association between high LDH-A and HIF-1α gene expression and poor outcome, and an inverse pattern of disease-free survival with immune-related gene expression (CD3E/CD4 and CD8A)." (PMID 30248111, 2018). "To elucidate the prognostic role of different subsets of CD4+ T cells in early breast cancer, we focus here on the CD4+ cells, forkhead box P3 (FOXP3) + CD4+ regulatory T cells (Tregs), and C-X-C motif chemokine ligand 13 (CXCL13)-positive CD4+ follicular helper T (Tfh) cells." (PMID 29482642, 2018). "Overall, 90% of patients with a CD4 count of 0 cells/μL – 200 cells/μL, 56% with 201 cells/μL – 500 cells/μL and 42% with 500 cells/μL – 1000 cells/μL exhibited advanced stages of breast cancer at the time of first staging, thereby demonstrating an inverse relationship." (PMID 31754516, 2018). "For example, combination therapy using the protein ligand of OX40, OX40L, fused to a cancer vaccine have been shown to reduce breast cancer metastasis, by enhancing antigen specific CD4+ and CD8+ T cell responses and inhibiting immunosuppressive Treg responses." (PMID 30073152, 2018). "Notably, among those with known CD4 counts, the percentage of patients who presented with advanced stages of breast cancer increased with declining CD4 counts." (PMID 31754516, 2018). "The age, gender, HIV status, CD4 count and tumour node metastases stage at presentation were recorded from the files of patients with histologically proven breast carcinoma, who had presented to the breast clinic at DGMAH from 01 January 2013 to 30 November 2017." (PMID 31754516, 2018). "Moreover, adoptively transferred human naive CD4+ T cells infiltrate human breast cancer orthotopic xenografts in a CCL18-dependent manner." (PMID 28290464, 2017). "Furthermore, the abundance of naive CD4+ T cells and Tregs is closely correlated, both indicating poor prognosis for breast cancer patients." (PMID 28290464, 2017). "Furthermore, TCR repertoire analysis suggests that Tregs in human breast cancer are mainly derived from naive CD4+ T cells." (PMID 28290464, 2017). "Here, we show that tumor-infiltrating naive CD4+ T cells and Tregs in human breast cancer have overlapping TCR repertoires, while hardly overlap with circulating Tregs, suggesting that intratumoral Tregs mainly develop from naive T cells in situ rather than from recruited Tregs." (PMID 28290464, 2017). "In another preclinical mouse model for metastatic breast cancer, the complement anaphylatoxin C5a receptor (C5aR) on immune cells facilitated metastasis to the lungs by suppressing local CD4+ and CD8+ T cell anti-tumor responses through recruitment of immature macrophages to the metastatic niche." (PMID 29037250, 2017). "For example, IL-4-expressing CD4+ T lymphocytes indirectly promoted invasion and metastasis of mammary carcinoma by activating epidermal growth factor signaling in mammary adenocarcinoma cells and changing the phenotype of tumor-associated macrophages from TAM1 to TAM2." (PMID 29037250, 2017). "Thus, in breast cancer there is a reduction of the normal CD8+: CD4+ T cell ratio due to lower levels of CD8+ T cell infiltration." (PMID 27777963, 2016).
breast cancer (continued). "In addition, KCFSs were found to have a significant impact on tumor size, apoptosis, and immune recruitment in a murine breast cancer model, resulting in increased apoptosis of tumor cells and increases in the CD4+ T cell population." (PMID 27199969, 2016). "A separate study utilizing a murine breast cancer model showed that kefir feeding prior to challenge with the tumor resulted in decreased size and increased apoptosis of the tumor, and that the levels of IgA+ cells and CD4+ T cells were also increased." (PMID 27199969, 2016). "In pulmonary metastatic model of breast cancer, Th2 CD4+ T lymphocytes that produce IL-4 and IL-13, M2-type TAMs and IMCs are activated and in turn produce EGF, thus resulting in activation of a paracrine-mediated enhancement of malignant cell invasion and dissemination." (PMID 27533463, 2016). "Interestingly, a comprehensive analysis of inflammatory immune characteristics of breast cancer also indicated a decrease in CD4 lymphocytes and an increase in CD8 lymphocytes." (PMID 27329588, 2016). "Notably, relative to IL-17+ cells (r = 0.379; P = 0.0093), Foxp3+ cells had a more significant correlation with CD4+ TILs (r = 0.639; P = 1.4 x10−10) in breast cancer patients." (PMID 25968569, 2015). "Furthermore, we obtained that breast cancer patients with high levels of CD4/CD8 ratio ( > 1.2) had significantly poor cancer-specific OS and RFS probabilities, which was very similar as those in CD4+ T cells." (PMID 25968569, 2015). "Besides the retrospective analyses of breast cancer patients, the results from the two breast cancer murine models showed that the proportion of CD8+ T cells was more dominant than CD4+ T cells in TILs in the early stages of tumor development." (PMID 25968569, 2015). "Notably, intra-tumoral CD4/CD8 ratio is still a significant and valuable clinical biomarker for identifying the risk for late-relapse and survival of breast cancer patients." (PMID 25968569, 2015). "Such a hypothesis is further supported by other results, including the finding that the amount of a specific set of CD4+ T cells, namely follicular helper T cells, predicts breast cancer survival." (PMID 25848820, 2015). "Despite the lack of statistical significance when considering IL 5 and IL 17 production separately, when we analyzed patients whose CD4+ T-cells produced IL-5 and/or IL-17, we did observe a significant impact on the overall survival (p = 0.01) in these elderly breast cancer patients." (PMID 26500775, 2015). "In addition to cell number increases, CD4+ T cells changed their dominant subsets from Th1 in the early stages to Treg and Th17 cells in the late stages of the breast cancer development." (PMID 25968569, 2015). "Therefore, improved understanding of the nature and functional roles of these CD4+ T cell subsets in tumor immunity during the course of breast cancer development is important for effective treatments of breast cancer." (PMID 25968569, 2015). "This has been shown in the context of CD4+ T lymphocytes and CD1α dendritic cells in axillary lymph nodes correlating with disease-free survival in breast cancer patients, to tumor-infiltrating CD3+ cells and CD8+ T lymphocytes in colon and bladder cancer respectively." (PMID 24733360, 2014). "Authors defend that the intensity of lymphocytic infiltrate and the CD4+/CD8+ ratio may represent important survival prognostic biomarkers for canine mammary carcinomas." (PMID 24672781, 2014). "This encouraging result obtained on ALC or T cell counts led the Blay/Ray-Coquard team to further document CD4 T cell counts in various populations of cancer patients, including breast cancer, and to further explore the diversity of the TCR repertoire in collaboration with ImmunID Technologies." (PMID 22383042, 2012). "Intriguingly however, they also suggest that breast cancer infiltration by CD4-/FOXP3+ lymphocytes might represent an independent favorable prognostic factor." (PMID 22471961, 2012).